CD24 (CD24 molecule)
Diseases named in the same sentence as CD24 in open-access papers (continued):
Sharing a sentence is not in itself a finding about the gene and the disease.
cancer (continued). "Future studies focusing on these genes may help to identify drugs that target the CD44+/CD24- subpopulation of cancer cells, as has been demonstrated recently using human mammary epithelial cells depleted of E-cadherin or overexpressing TWIST." (PMID 20691079, 2010). "However, in contrast to CD44, only a small portion of CD24+ cells were positive in HNSCC cancer cells in our study." (PMID 19602232, 2009). "Note that all luminal cell types contain disproportionately higher levels of CD44-/CD24+ cells, and this population may contain cancer progenitor cells corresponding to luminal type of tumors." (PMID 17062128, 2006). "Therefore, CD24 is expressed in CSCs of both solid and hematological malignancies, making it a potential surface marker for CSCs across various types of malignant tumors and contributing to the occurrence and progression of these cancers." (PMID 40486886, 2025). "In addition to the role of CD24 in cancer progression, recent research has shed light on the function of CD24 as a “don’t eat me” signaling molecule that interacts with macrophage Siglec-10, triggering a signaling cascade that inhibits macrophage-mediated phagocytosis." (PMID 40783744, 2025). "Understanding the mechanisms that CD24 induces chemoradiotherapy resistance may allow us to develop new promising therapeutic strategies to enhance the efficacy of chemoradiotherapy and improve clinical outcomes in the treatment of cancer patients." (PMID 40486886, 2025). "The absence or presence of CD24 may affect the composition of the membrane raft, which in turn affects transcription factors and signaling pathways, which play a key role in the body's ability to fight off cancer cells." (PMID 38914670, 2024). "CD24 is a prominent innate immune checkpoint that may be a useful target for cancer immunotherapy." (PMID 38279998, 2024). "However, whether sialylation governs the subcellular localization of CD24 in cancer remains unclear, and the impact of CD24 expression and localization on the clinical prognosis of cancer remains controversial." (PMID 39791710, 2024). "Therefore, we wondered whether miR-204 has a functional role in VM formation in MDA-MB-231 and Hs-578t cancer stem-like cells (CD44+/CD24−)." (PMID 38392969, 2024). "In addition to CD44, CD24 can also be used to identify the cancer stem cells (CSCs)." (PMID 38279998, 2024). "However, the regulatory mechanisms controlling the subcellular localization of CD24 in cancer remain unclear." (PMID 39791710, 2024). "Furthermore, CD24 is a novel target for cancer-related immunotherapy." (PMID 38217543, 2024). "Although it has been thought that cancer immunotherapy that targets the CD24/Siglec-10 signal pathway is a promising approach, further research is required due to the intricacy of the signaling system and the widespread expression of CD24/Siglec-10 in many normal cell types." (PMID 38279998, 2024). "In fact, circulating autologous CD14+ cells are the progenitor of resident NLCs and the baseline upregulation of Siglec‐10 might reflect the M2‐like immunosuppressive profile of NLCs within TME, where they interact with CD24+ cancer cells, receiving anti‐phagocytic stimuli." (PMID 37654003, 2023). "Therefore, CD24 inhibition is a promising strategy for cancer therapy." (PMID 37894750, 2023). "Consequently, targeting CD24 emerges as a promising therapeutic strategy for cancer treatment." (PMID 38313430, 2023). "Besides, increased expression of CD24 is usually tied with a more aggressive course of cancers." (PMID 37919766, 2023). "Therefore, investigators present a novel molecular mechanism responsible for Hh signaling-mediated cancer cell migration and invasion via CD24 expression, which may be useful for the treatment of solid cancers." (PMID 37919766, 2023). "Thus, engaging CD24-signaling may provide protection from inflammation and/or autoimmune disease following acute tissue injury induced by effective cancer immunotherapy." (PMID 37346042, 2023).
cancer (continued). "Therefore, because of cancer related interactions between CD24 and its identified ligands, it seems that inhibition of the interactions may be useful in anti-cancer therapies." (PMID 37919766, 2023). "CD24 overexpression has been observed in a variety of cancer cell lineages, such as in breast, ovarian and prostate cancer, bladder, lung and hepatocellular carcinoma, and non-Hodgkin B cell lymphoma, and is considered a significant marker for cancer diagnosis and prognosis." (PMID 36294907, 2022). "In addition, several other anti-phagocytic surface proteins (immune checkpoint) such as PDL1, LILRB1, B2M, and CD24 have also been found to inhibit the phagocytosis of cancer cells both in the in vitro co-culture of cancer cells with macrophages as well as in vivo." (PMID 36679900, 2022). "Indeed, ex vivo, these peptides were not toxic to lymphocytes derived from healthy volunteers; (b) the target (CD24) is expressed almost exclusively in cancer cells; (c) the lentiviral vectors are self-inactivating and were shown to exert no genotoxicity in 43 gene therapy studies." (PMID 33958722, 2021). "Similarly, ALK4L75A-Fc reduced cell surface levels of the cancer stem cell-associated marker CD44 in MDA-MB-231 and MDA-MB-468 cells treated with 2-DG or thapsigargin, while increasing expression of the CSC contraindicator CD24 in MDA-MB-231 cells." (PMID 33187540, 2020). "Therefore, non-amplification mechanisms, such as activation of HIF1α, may work either independently or in concert with gene amplification to drive a high level of CD24 expression in cancer." (PMID 31244889, 2019). "Therefore, it is of considerable interest to determine whether CD24 is amplified in human cancers, and if so whether such amplification corresponds to CD24 overexpression and clinical outcome." (PMID 31244889, 2019). "Similarly, the expression of CD24 on other human tumors offers the prospect for Zika virus treatment of other malignancies, potentially broadening the relevance of these findings to include not only pediatric cancers, but adult tumors as well." (PMID 30044847, 2018). "However, the exact mechanism by which CD24 results in poor prognosis in various cancers remains unknown and it needs to be further elucidated." (PMID 29416796, 2018). "However, a recent study revealed that CD24 suppresses the immune response through interaction with Siglec protein expressed on immune cells, and this may suggest the possible contribution of CD24-Siglec pathway to the cancer immune escape." (PMID 26444008, 2015). "Although there was little overlap between CD90 and CD24, interestingly, CD90+ cells were clustered in three to five layers around CD24+ malignant ducts, suggesting that CD90 may play a critical role in cancer-associated fibroblasts which can promote pancreatic tumorigenesis and development." (PMID 25536077, 2014). "For this reason the cancer stem cell-like phenotype commonly observed in IBC tumors may contribute to their aggressive nature but also may offer itself novel therapeutic strategies to the selective targeting of CD44+/CD24− CSCs from bulk tumors." (PMID 24970653, 2014). "Although no markers, single or combined, could be defined unequivocally to specifically identify cancer stem cells in a given solid tumor so far, our data indicate that CD24-positive subpopulation might be the most likely stem-like cells that are related to ccRCC metastasis." (PMID 23442546, 2013). "Thus, the cytoplasmic expression of CD24 could be used as a specific marker to predict the survival rates and recurrence of cancer." (PMID 23509802, 2013). "However, much remains to be learned about the activity of CD24 in the context of cancer." (PMID 23533633, 2013). "In addition, the interaction of cancer cells with P-selectin via CD24 may be an important adhesion pathway involved in cancer metastasis and progression." (PMID 23946784, 2013).
cancer (continued). "The differential expression of hypoxia marker HIF-1α in CD44+CD24-/low tumors is in accordance with the current knowledge regarding relationship between microenvironmental factor such as hypoxia or anoxia states with maintenance and propagation of cancer stem cells." (PMID 21824412, 2011). "Moreover, the obvious heterogeneity of cells with various CD44/CD24 expression within individual tumors may be indicative of a cancer stem cell subpopulation giving rise to more differentiated and committed cell populations." (PMID 18559090, 2008). "Thus, distant metastasis in patients with elevated levels of CD44+/CD24- cells may be related to enhanced invasiveness of cancer cells." (PMID 17062128, 2006). "A notable decrease in cell growth, the CD44+CD24‐ population, and the EMT status was observed in the recipient cancer cells." (PMID 40059964, 2025). "It should be noted that the same proteins (CD9, CD24, CD63, CD81, MMP9) were common to exosomes of cancer cells and primary cells." (PMID 40310419, 2025). "In this work, we found that by isolating EVs enriched from CD24+ and HER2+ EV sub-types, we can gain a more comprehensive view of a developing cancer than is possible with either single EV sub-population, and thus make more accurate clinical classifications." (PMID 40405296, 2025). "The CD24-specific antibody component activates macrophages, whereas the MMAE payload induces G2/M arrest and apoptosis, effectively killing cancer cells." (PMID 40806691, 2025). "Subsequently, we analysed the expression levels of these genes across 33 types of cancer and found that AXL, MERTK, TYRO3, CD24, HAVCR2 and CD47 exhibited higher expression levels, while TIMD4 and HAVCR1 showed relatively lower expression." (PMID 40576208, 2025). "The epithelial OC origin of the PDC2 and PDC3 samples was confirmed by the expression of OC-specific markers PAX8 and CD24, epithelial makers MKI67, EPCAM, KRT8 and KRT18 and cancer stem cell markers such as CD44 and ROR1." (PMID 39482470, 2025). "We demonstrate expression of the markers CD24, CD44, CD133 and ALDHA1A, which are well known to characterize cancer stem cells." (PMID 41310103, 2025). "This was further supported by the significant changes in cancer stem cell (CSC) marker expression (CD133, CD24, EPCAM) corresponding to MORF4L1 expression levels." (PMID 39757177, 2025). "The topmost expressed epitopes in ascitic fluid EVs were CD326/EpCAM, CD133/1, HLA-DR, CD24 and CD44, which are cancer-related markers." (PMID 40259212, 2025). "Some cancer cells express “don't eat me” signal ligands such as CD47 and CD24, which can be recognized by TAM receptors such as SIPR1a (for CD47) and SIGLEC10 (for CD24), effectively blocking the attack from TAMs." (PMID 40083710, 2025). "Current CSC markers, including CD44, CD24, and ALDH, exhibit variable expression patterns across different cancer types and lack specificity, complicating the prediction of treatment responses." (PMID 40821110, 2025). "Expression levels of both CD24 and CD47 in the cancer population were higher than those in the normal population." (PMID 41354057, 2025). "CD24 is a GPI-anchored membrane protein that is considered a stem cell marker in many human malignancies and has recently emerged as a target for cancer immunotherapy." (PMID 39136818, 2025). "Simultaneously, SIRT1-mediated activation of the CD24/Siglec-10 axis suppresses the activity of CD8+ T cells, crucial immune cells responsible for targeting and killing cancer cells." (PMID 40330466, 2025). "CD24 is a small, highly glycosylated GPI-anchored protein involved in immune cell differentiation and inflammation; when overexpressed on cancer cells, it functions as a “don't-eat-me” signal via Siglec-10, suppressing macrophage and NK-cell clearance." (PMID 41281650, 2025).
cancer (continued). "A key result from the profiling study showed that exosomal EpCAM and CD24 levels were significantly higher in ovarian cancer patient samples, and pairing these protein profiles increased diagnostic accuracy to 97% for distinguishing cancer from non-cancer controls." (PMID 40801693, 2025). "In the tumor microenvironment, cancer cells can inhibit macrophage phagocytic activity through the expression of “don’t-eat-me” checkpoint proteins (i.e., CD47 and CD24)." (PMID 38690738, 2024). "The relationship between CD24 and NKG2D in the context of cancer involves a complex modulation of immune responses." (PMID 38881902, 2024). "Intriguingly, we also found that the cancer stem cells (CSC) score, calculated using common CSC markers (EPCAM, CD24, KRT19, SOX9, PROM1, CD44, THY1, CD47), was significantly higher in the EMT-subtype." (PMID 39095854, 2024). "Expression results also showed that castration-rebound VCaP-NURR1 tumors expressed enhanced levels of phenotypic markers of EMT (reduced E-cadherin and increased vimentin levels) and cancer stemness (increased CD44 and Oct4a, and decreased CD24 levels)." (PMID 38531859, 2024). "LCSCs are characterized by specific surface markers, such as CD133, CD90, the epithelial cell adhesion molecule (EpCAM), CD24, and CD13, which distinguish them from the bulk of differentiated cancer cells." (PMID 39769068, 2024). "In 65% of cancers, such as THCA and BRCA, high levels of CD24 were present in the cytoplasm and cell membrane in more than 80% of cases." (PMID 39791710, 2024). "In specific cancer cells like A125 and MDA-MB-435S, CD24 was observed to recruit β1 integrin into lipid rafts." (PMID 38881902, 2024). "Only two transcriptomic signatures reported were composed of co-expressed genes: the cancer stem cell markers CD44, CD24, and ESA; and TSPAN8 and SOX9." (PMID 39200223, 2024). "Phagocytosis checkpoints like CD47, CD24, MHC-I, and PD-L1 play a critical role in cancer immunotherapy by acting as escape signals from immunogenic cells, thereby weakening the immune activity against tumors." (PMID 39726713, 2024). "In conclusion, we examined the associations of several reproductive variables with the expression of stem cell markers CD44, CD24, and ALDH1A1 in cancer-free women." (PMID 38577336, 2024). "We previously demonstrated that CD44+CD24− cancer cells are enriched in basal-like tumors compared with other breast cancer subtypes and that CD44+CD24− cancer cells have heightened IL-6/JAK2/STAT3 signaling activity compared with other tumor cells." (PMID 38297352, 2024). "We observed that the M2-like TAMs upregulated the expression of CD24, CD47 and ICAM1 (markers enriched in cluster C6 cancer cells) in MHCC7L HCC cells." (PMID 38169544, 2024). "Our study is the first to date to explore associations of several reproductive variables with the expression of breast stem cell markers CD44, CD24, and ALDH1A1 in cancer-free women." (PMID 38577336, 2024). "This highlights the importance of exploring the roles of CD24 and NKG2D in cancer immunity and the potential for therapeutic interventions that modulate their activity." (PMID 38881902, 2024). "Therefore, CD24 may serve as an attractive target for cancer therapy." (PMID 38168654, 2024). "Herein, a peptide-antibody combo-supramolecular in situ assembled CD47 and CD24 bi-target inhibitor (PAC-SABI) is described, which undergoes biomimetic surface propagation on cancer cell membranes through ligand-receptor binding and enzyme-triggered reactions." (PMID 38971872, 2024). "The combinational therapy was found to target cancer stem cells, as suggested by the reduction of cancer stemness factors, such as DCLK-1, CD24, Lgr5, CD29, and CD44, and the colonosphere formation." (PMID 36765950, 2023). "CD24 enhances the upregulation of STAT3-dependent genes, such as cyclin D1, survival protein, and MCL-1, thus promoting survival and proliferation of cancer cells." (PMID 38137380, 2023).
cancer (continued). "We further investigated the expression and distribution of proliferation-related (CDK4, MKI67) and cancer-related epithelial (KRT15, CD24) cell marker genes among each cluster." (PMID 36811599, 2023). "For instance, recent studies have shown that CD24 promotes immune evasion by interacting with Siglec-10 in tumors, and FGL1-LAG-3 interaction mediates T cell suppression in various cancers." (PMID 37566630, 2023). "Flow cytometric analysis showed that the population of POU5F1-positive cells was also detected in 2DOs as cancer cells and differed from previously reported CRC stem cell marker-positive cells, including those with the markers, CD133, CD44, CD24, and LGR521." (PMID 37996567, 2023). "In this review, we summarized and discussed the latest advancements and insights into CD24 and CD200 as emergent immune checkpoint moieties, further delving into their therapeutic potentials for cancer treatment." (PMID 37894750, 2023). "For HCC model, markers including CK8, CK18, HepPar-1, Arg-1, AFP, HSP70, GPC3, CEA, CD24, CD133 and EpCAM can be used to identify cancer type and cancer progression." (PMID 37188191, 2023). "In addition, the absence or presence of CD24 may influence membrane raft composition and thereby affect transcription factors and signaling pathways to play a critical role in the human body’s ability to ward off cancer cells." (PMID 37919766, 2023). "In our study, we confirmed the presence of cancer cells by assessing the expression of a group of CD44(+) and CD24(+) receptors." (PMID 38201547, 2023). "As previously reported, the CD24 and CD44 cell surface proteins have been recognized as CSC markers in other cancers." (PMID 36737794, 2023). "Keisuke Taniuchi discovered that intracellular CD24 can interact with phosphorylation-dependent endonuclease G3BP to inhibit the invasiveness and metastasis of cancer cells." (PMID 38137380, 2023). "CD24, a GPI-anchored glycoprotein, has been shown to interact with several signalling and cross-linking molecules, contributing to cancer progression." (PMID 38137380, 2023). "As putative CSC properties play a crucial role in cancer progression, we first analyzed the expression of the pancreatic CSC markers CD44, CD24, CD133, and c-Met." (PMID 37537633, 2023). "In addition, Wnt/β-catenin pathway could regulate the expression of CD24 in cancer cells." (PMID 37359556, 2023). "In their work, the authors analyzed the presence of other cancer stem cell markers, including CD44+/CD24+/EPCAM+ and CD133+." (PMID 37371030, 2023). "CD24 is an epithelial differentiation marker that is reduced during EMT and is found in low or negligible levels in cancer stem cells." (PMID 36979915, 2023). "CD24 is abundantly expressed and is considered a putative cancer stem cell (CSC) marker in human cancers." (PMID 37894750, 2023). "Phagocytosis checkpoints, such as CD47, CD24, MHC-I, PD-L1, STC-1 and GD2, have emerged as essential checkpoints for cancer immunotherapy by functioning as “don’t eat me” signals or interacting with “eat me” signals to suppress immune responses." (PMID 36882399, 2023). "The results showed that the mRNA expression of CD24, CD47, and CD155 was presented in these four cancer types, which was consistent with TCGA results." (PMID 38016957, 2023). "Drawing from the multiple scientific studies on cancer immunotherapy, we narrowed our focus to CD24 and CD200 as immune checkpoint molecules that are overexpressed in cancer cells." (PMID 37894750, 2023). "Primary culture of the malignant tumors of the converted cells exhibited the elevated expression of CSC related genes CD44, CD24 and EPCAM maintaining the expression of stemness genes." (PMID 37181678, 2023). "In the cancer field, previous studies have also demonstrated that surface nano-patterns and interfacial geometry enhance CD44+/CD24- ESA+ and other stem markers, highlighting the relevance of surface topographies to enrich CSC populations for isolation." (PMID 36968199, 2023).